SMAD3 (SMAD family member 3)
Diseases named in the same sentence as SMAD3 in open-access papers (continued):
Sharing a sentence is not in itself a finding about the gene and the disease.
osteoporosis (10 papers, 2019 to 2024). A condition of reduced bone mass, with decreased cortical thickness and a decrease in the number and size of the trabeculae of cancellous bone (but normal chemical composition), resulting in increased fracture incidence. "Such clustering results are interesting as TGFBR1, TGFBR2 and SMAD3 formed a cluster that showed enhanced expression in primary osteoporosis." (PMID 36443839, 2022). "Enhanced expression of the genes mediating TGF-β-mediated SMAD3 signaling and the genes encoding TGF-β superfamily antagonists served as significant features to osteoporosis." (PMID 36443839, 2022). "To identify mechanisms of SPTBN1 in osteoporosis, we explored pathways related to SPTBN1 by STRING website and found that SPTBN1 may associate with TGF-β/Smad3 and STAT1/Cxcl9 signaling pathways." (PMID 33816505, 2021). "Riveting on our findings, up‐regulation of miR‐497 or down‐regulation of LRG1 could activate TGF‐β signalling pathway as accompanied by increased TGF‐β1, Smad3, Smad4 and p‐Smad2/3 protein expression and reduced Smad7 protein expression in osteoporosis." (PMID 32975015, 2020). "Therefore, SPTBN1 may suppress primary osteoporosis of osteoblasts through Smad3/TGF-β and STAT1/Cxcl-9 signaling pathways." (PMID 33816505, 2021). "In the glucocorticoid-induced osteoporosis zebrafish model, this Traditional Chinese Medicine can promote collagen synthesis through the TGF-β/Smad3 signal pathway and inhibit inflammatory reactions via NF-κB and AP-1 pathways." (PMID 36675272, 2023). "Taken together, these results suggested that SPTBN1 suppressed primary osteoporosis by facilitating the proliferation, differentiation, and inhibition of apoptosis in osteoblasts via the TGF-β/Smad3 and STAT1/Cxcl9 pathways." (PMID 33816505, 2021). "The results showed that overexpression of SPTBN1 significantly suppresses the development of primary osteoporosis by modulating VEGF, TGF-β/Smad3, and STAT1/Cxcl9 signaling pathways." (PMID 33816505, 2021). "Thus, SPTBN1 may regulate osteoblast by TGF-β/Smad3 and STAT1/Cxcl9 signaling pathways in osteoporosis." (PMID 33816505, 2021).
Parkinson disease (10 papers, 2011 to 2025). A progressive degenerative disorder of the central nervous system characterized by loss of dopamine producing neurons in the substantia nigra and the presence of Lewy bodies in the substantia nigra and locus coeruleus. "Though, Smad3 deficiency manifests phenotypic symptoms, such as curvature of the spine (kyphosis) and resting tremor that is characteristic of parkinsonism." (PMID 21995845, 2011). "Smad3 deficient mice represent an interesting model to study parkinsonism due to the effects on nigrostriatal dopaminergic neurodegeneration and α-synuclein aggregation, where overexpression of α-synuclein may also play a role on hippocampal neurogenesis." (PMID 24330661, 2013). "Smad3 deficiency may correlate with early signs of parkinsonism, and alterations in TGFβ-Smad3 signalling may contribute to the pathogenesis of parkinsonism." (PMID 21995845, 2011). "Smad3 deficiency promotes strong catabolism of DA in the striatum (ST), decrease trophic and astrocytic support to dopaminergic neurons and may induce α-synuclein aggregation, which may be related to early parkinsonism." (PMID 21995845, 2011). "The molecular events detected in Smad3-/- mice were highly suggestive of early signs of parkinsonism." (PMID 21995845, 2011). "We further assessed Smad3 expression in other brain areas related to parkinsonism, such as the ST and the motor cortex." (PMID 21995845, 2011). "Moreover, TGF-β/Smad3 intracellular signalling was recently shown to modulate GABA neurotransmission in the context of parkinsonism and cognitive alterations." (PMID 31963327, 2020). "Recent research has also highlighted the role of TGF‐β/Smad3 signaling in modulating GABA neurotransmission, particularly in the context of parkinsonism and cognitive alterations." (PMID 40831324, 2025).
Aortic dissection (9 papers, 2014 to 2026). Aortic dissection refers to a tear in the intimal layer of the aorta causing a separation between the intima and the medial layers of the aorta. "Also it has been supported that individuals who carry pathogenic variants in SMAD3 are more prone to early aortic dissection and/or rupture, even in a mildly dilated aorta." (PMID 32597575, 2020). "However, mutations in SMAD3 have been identified in up to 2% of patients with familial thoracic aneurysms leading to acute aortic dissection." (PMID 29073282, 2017). "LDS is caused by an abnormality in transforming growth factor‐β (TGF‐β) signaling pathway‐related genes, and fatal aortic dissection (AD) and rupture often occur at a younger age and with smaller vessel diameters than MFS, particularly in Type 1–3 LDS (TGFBR1/2: LDS1/2; SMAD3: LDS3)." (PMID 39130808, 2024). "Of individuals with SMAD3 variant associated AOS, who suffered aortic dissection, half had presented with dissection and did not have a genetic diagnosis prior to dissection." (PMID 36312254, 2022).
breast tumors (9 papers, 2011 to 2025). "During breast tumorigenesis it seemed necessary to turn off TGF-β-mediated Smad2 responses while retaining the Smad3 responses for further progression of breast tumors of triple negative type." (PMID 31798766, 2019). "According to COSMIC, no SMAD3 mutations were reported based on 48 breast tumors screened while two SMAD3 homozygous mutations were identified from 38 colorectal tumors." (PMID 21835029, 2011). "Considering the significant correlation between high fibronectin levels and poor overall survival (OS) outcome in basal breast tumors, this suggested that fibronectin may represent a critical downstream regulator of the TGFβ/Smad3/COX-2 effects on cancer stemness." (PMID 28054666, 2017). "In primary breast tumors, YAP inhibits Smad3 activity, which in turn promotes the self-renewal of tumor stem cells." (PMID 40673277, 2025). "Using publically available online tissue expression data, SMAD3 and SMAD4 expression in breast tumors versus normal breast tissue were assessed using two independent samples t-test and Levin's test for the equality of variance." (PMID 21835029, 2011). "TrkB is capable of binding to SMAD2, SMAD3, and SMAD4 in TrkB-expressing human breast tumors." (PMID 32340410, 2020). "In addition, the expression levels of p-Smad2, p-Smad3, and Smad4 in the nucleus of MCF-7 breast tumor cells were measured by immunofluorescence microscopy, and we found that SSA could reduce the level of p-Smad2/3 in the nucleus with or without the presence of TGFβ1." (PMID 26769851, 2016).
endometrial cancer (9 papers, 2016 to 2024). Primary or metastatic malignant neoplasm involving the endometrium (mucous membrane that lines the endometrial cavity). "The results obtained by Bokhari and Syed suggested that SB and FC extracts prevent endometrial cancer cell proliferation, invasion, and metastasis by inhibiting TGFβ/SMAD3-mediated EMT and by downregulating TGFβ-activated integrins and FAK expression." (PMID 33498521, 2021). "We have previously shown that treatment with activin B phosphorylates/activates SMAD2 and SMAD3 in type II human endometrial cancer cells." (PMID 27223076, 2016). "Similarly, our study showed that 10 μM of ISL reduced TGF-β1-induced expression of N-cadherin, vimentin, and p-Smad3, while increased E-cadherin expression, and finally inhibited the migration of endometrial cancer cells." (PMID 33799801, 2021). "Together, these data indicate that ISL might reverses EMT through a TGF-β1/Smad3/TWIST1/2 dependent signaling pathway in human endometrial cancer cells." (PMID 33799801, 2021). "Furthermore, we observed that cg24032190 of SMAD3 is 60% hypermethylated in endometrial cancer in both Taiwanese patients and TCGA datasets." (PMID 33036415, 2020). "However, the result was the opposite in endometrial cancer, where 60% (9/15) of patients showed SMAD3 hypermethylation." (PMID 33036415, 2020). "In endometrial cancer, MIR210HG enriched genes in the Wnt and TGF-β/Smad3 signaling pathways, thereby enhancing the development of cancer." (PMID 38474063, 2024). "In this study, we observed abnormal differentiation of the endometrium and transformation into endometrial cancer following conditional ablation of the downstream effectors of TGFβ signaling, SMAD2 and SMAD3." (PMID 36906706, 2023). "On the other hand, a study has been published presenting that decreased mRNA levels of SMAD2, SMAD3, and SMAD4 are frequent events, respectively in 71.4%, 78.6%, and 78.6% of analyzed endometrial cancer samples." (PMID 34501347, 2021). "High S100A2 expression has been associated with the regulation of tumor cell proliferation and invasion through the enhancement of PI3K/AKT activation and functional interaction with SMAD3; however, whether S100A2 expression has prognostic value in endometrial carcinoma has remained unknown." (PMID 35042454, 2022). "The results of this study demonstrated that ISL could reverse TGF-β-induced endometrial cancer cell migration through inhibition of TGF-β/Smad signaling pathway with subsequent increased E-cadherin expression and reduced N-cadherin, vimentin, α-SMA, p-Smad3, and TWIST1/2 expression." (PMID 33799801, 2021).
esophageal squamous cell carcinoma (9 papers, 2015 to 2026). Esophageal squamous cell carcinoma (ESCC) is a type of esophageal carcinoma (EC) that can affect any part of the esophagus, but is usually located in the upper or middle third. "Besides, inhibition of Smad3-dependent long non-coding RNA erb-b2 receptor tyrosine kinase 4 intracellular domain fragment (Erbb4-IR) suppresses the proliferation of esophageal SCC by upregulating the tumor suppressor gene miRNA-145 to activate cancer cells apoptosis." (PMID 37205317, 2023). "In addition, a novel Smad3-dependent long non-coding RNA Erbb4-IR showed various actions in prostate and esophageal squamous cell carcinoma, where one of the actions is to inhibit apoptosis by downregulating tumor suppressor miRNA-145, thus promoting cancer cell proliferation." (PMID 34299192, 2021).
nasopharyngeal carcinoma (9 papers, 2019 to 2022). A carcinoma arising from the nasopharyngeal epithelium. "MALAT1 promotes EMT of nasopharyngeal carcinoma cells through de-repressing Capn4 by sponging miR-124 and mediates TGF-β1-induced EndMT by regulating TGFBR2 and SMAD3 through miR-145 in endothelial progenitor cells (EPCs)." (PMID 30871555, 2019). "EBV drives NPC metastasis through EBV-encoded LMP1-mediated metabolic reprogramming via activation of IGF1-mTORC2 signaling and nuclear acetylation of the Snail promoter by PDHE1α, LMP1 upregulates calreticulin to induce EMT via the TGF-β/Smad3/NRP1 pathway in nasopharyngeal carcinoma cells." (PMID 35388172, 2022).
scleroderma (9 papers, 2013 to 2025). Scleroderma is a rare autoimmune connective tissue disorder characterized by abnormal hardening of the skin and, sometimes, other organs. "In skin fibroblast from scleroderma patients, nuclear localization of active SMAD3 with elevated TGFβ gene expression was observed." (PMID 40261983, 2025). "EchA treatment reduces the number of activated myofibroblasts expressing α-SMA, vimentin, and phosphorylated Smad3 in bleomycin-induced scleroderma." (PMID 33922418, 2021). "A previous study showed there are fewer myofibroblasts in bleomycin-induced scleroderma lesions for Smad3-/- mice, further verifying the necessity of SMAD3 for fibroblast proliferation." (PMID 33322749, 2020). "WKYMVm-treated scleroderma skin tissues displayed reduced numbers of myofibroblasts expressing α-smooth muscle actin, Vimentin, and phosphorylated SMAD3." (PMID 31552041, 2019). "In our study, WKYMVm treatment led to decreased production of myofibroblasts positive for α-SMA, Vimentin, and phospho-SMAD3 through an Fpr2-dependent mechanism in the scleroderma model." (PMID 31552041, 2019). "The number of Vimentin+p-SMAD3+ myofibroblasts increased in the BLM-induced scleroderma model, and WKYMVm treatment markedly reduced the BLM-induced increase of Vimentin+p-SMAD3+ cell number." (PMID 31552041, 2019). "On the other hand, the involvement of Smad3 is observed in fibrosis in many animal models of scleroderma, cystic fibrosis." (PMID 26997760, 2016). "Moreover, increased Smad2 and Smad3 phosphorylation by TGF-β was observed in scleroderma fibroblasts." (PMID 31937306, 2020). "Moreover, elevated Smad3 was observed in scleroderma fibroblasts which are characterised by the excessive synthesis and accumulation of matrix proteins." (PMID 26507880, 2016). "Moreover, 3 μM SIS3 completely diminished the constitutive phosphorylation of Smad3 as well as the excessive type I procollagen expression in scleroderma fibroblasts." (PMID 26997760, 2016). "SIS3 may reduce the upregulated expression of type I collagen through the inhibition of phosphorylated Smad3 in scleroderma fibroblasts." (PMID 26997760, 2016). "The mechanism by which HF reduces fibrosis was recently elucidated in a mouse model for scleroderma (dermal fibrosis), where a low dose of halo blocked TGF-β mediated SMAD3 activation in fibroblasts." (PMID 24358159, 2013). "Furthermore, WKYMVm treatment did not reduce the numbers of Vimentin+ or Vimentin+p-SMAD3+ myofibroblasts in the scleroderma skin of Fpr2 KO mice, in contrast to the significant inhibition of those in the scleroderma skin of wild type mice." (PMID 31552041, 2019).
viral infection (9 papers, 2011 to 2025). "In the present study, SARS-CoV-2 reduced SMAD3 expression, which is consistent with previous findings on the decreased expression of SMAD3 during viral infection to overtake the host innate antiviral mechanism." (PMID 33521069, 2020). "Besides, we also found several instances including differentially expressed C4B gene and SMAD3/SMAD4/JUN/FOX complex to explore potential possible mechanistic details of how non-tumor individuals who are not susceptible fend off viral infections." (PMID 38752789, 2024). "Mechanistically, HBT binds to the NA protein of the influenza virus, reducing viral infection and the activation of the TGF-β/Smad3 pathway, thereby mitigating the formation of lung injury and PF." (PMID 41011177, 2025). "In conclusion, aging and exposure to viral infections may induce OPN release and consequently modulate inflammation and TGF-β1/Smad3-related remodeling, contributing to the development of LOA." (PMID 32009132, 2020). "As for Smad3 expression, some human studies showed an obvious upregulation in expression upon viral infection, while others showed no change from healthy controls." (PMID 28506310, 2017).
Cirrhosis (8 papers, 2014 to 2025). A chronic disorder of the liver in which liver tissue becomes scarred and is partially replaced by regenerative nodules and fibrotic tissue resulting in loss of liver function. "In this setting, there is likely to be apoptosis and fibrosis, while low expression of PPARα and NR1H4TGFβ activates the SMAD3-mediated TGFβ pathway, leading to the progression of BA and cirrhosis." (PMID 36090996, 2022). "IHC staining showed that TBR2 and Smad3 expression were restored by VD treatment in both liver tissues from cirrhosis and HCC patients, whereas β-catenin expression was repressed by VD treatment in liver tissues from HCC patients." (PMID 27456065, 2016). "Cirrhosis-related factors, such as transforming growth factor β1 (TGF-β1), type 1 collagen (collagen-1), α-smooth muscle actin (α-SMA), and P-Smad3/Smad3 expression levels, were evaluated using real-time polymerase chain reaction and western blot assays." (PMID 25425284, 2014). "Additionally, metformin delayed the progression of cirrhosis by regulating the activation and proliferation of hepatic stellate cells (HSCs) via the TGF-β1/Smad3 and succinate-GPR91 pathways." (PMID 38192642, 2023).
Loeys-Dietz syndrome type 3 (8 papers, 2018 to 2026). "SMAD3 mutations have been linked to the syndromic disease Aneurysms Osteoarthritis Syndrome that is characterized by large vessel aneurysms that primarily result from loss of SMC and related structural matrix components." (PMID 30307970, 2018). "Limited data on patients with SMAD3 pathogenic variants are available at present with reports of sudden cardiac death and left ventricular hypertrophy in one of the initial series on Aneurysm Osteoarthritis Syndrome due to SMAD3 pathogenic variants." (PMID 29717556, 2018). "Also, SMAD3 mutations have been linked to the syndromic disease Aneurysms Osteoarthritis Syndrome." (PMID 30307970, 2018). "For example, a previous patient with Loeys-Dietz syndrome type 3 with a SMAD3 LPV fulfilled both the old and revised Ghent criteria." (PMID 40169830, 2025).
pancreatic ductal adenocarcinoma (8 papers, 2011 to 2025). An infiltrating adenocarcinoma that arises from the epithelial cells of the pancreas. "In pancreatic ductal adenocarcinoma, Smad3 and Smad2 exert opposite effects on growth and cellular migration, and in primed pluripotent cells, Smad3 was shown to be dispensable for the maintenance of the undifferentiated state." (PMID 25878769, 2015). "Also, HUCMSCs-derived exosomal miR-145-5p inhibits pancreatic ductal adenocarcinoma cell proliferation, invasiveness, and their resistance to apoptosis by down-regulating Smad3 expression." (PMID 35428780, 2022). "In pancreatic ductal adenocarcinoma (PDAC), circEIF3I acts as a molecular scaffold that interacts with SMAD3 and AP2A1 to form a ternary complex, facilitating the recruitment of SMAD3 in early endosomes." (PMID 40356340, 2025). "It was reported upregulated SMAD3 promotes EMT and predicts poor prognosis in pancreatic ductal adenocarcinoma." (PMID 27601936, 2016). "SMAD3 was found to promote EMT and predict prognosis in pancreatic ductal adenocarcinoma." (PMID 27601936, 2016).
rheumatoid arthritis (8 papers, 2013 to 2022). A chronic, systemic autoimmune disorder characterized by inflammation in the synovial membranes and articular surfaces. "TGF-β/Smad3 signaling pathway is activated in synovium of patients with rheumatoid arthritis, being involved with Smad7 deficiency, and enhancement of Th17 and Th1 immune response." (PMID 34526039, 2021). "Recently, a patient with the SMAD3 mutation was demonstrated to have multiple aneurysms and rheumatoid arthritis." (PMID 26221609, 2015). "Lastly, ASH1L, FOXP3 and SMAD3 are downregulated in peripheral CD4+ T cells from patients with rheumatoid arthritis." (PMID 28598443, 2017). "The data selected based on the results, which were obtained from the likelihood ratio test, revealed that SMAD3 and STAT3 may be possible diagnostic biomarkers for rheumatoid arthritis." (PMID 33362761, 2020). "Furthermore, ASH1L, SMAD3 and FOXP3 are all downregulated in CD4+ T cells from PBMCs of patients with rheumatoid arthritis, indicating the potential significance of ASH1L/SMAD3/FOXP3 pathway in human autoimmune pathogenesis." (PMID 28598443, 2017).